IL13 (interleukin 13)
Diseases named in the same sentence as IL13 in open-access papers (continued):
Sharing a sentence is not in itself a finding about the gene and the disease.
COVID-19 (continued). "Overall, the data suggest a complex interplay of type 2 cytokines in COVID-19 severity, though little is known about IL-4, as distinct from IL-13, or the kinetics of the 2 cytokines effects in the context of early viremia and longer inflammatory processes." (PMID 40854598, 2025). "The GO terms discovered through DIABLO highlighted a link between Interleukin-4 and Interleukin-13 signaling and COVID-19 severity." (PMID 40429886, 2025). "Th22 cells play a re-epithelializing role through IL-22 production and both IL-13 and IL-22 are protective factors during acute and persistent COVID-19, promoting tissue protection and regeneration." (PMID 41181095, 2025). "In COVID-19, IL-13 reduces the viral load and cell to cell transmission by reducing the expression of ACE2, effectively weakening the infection and replication ability of COVID-19." (PMID 40495223, 2025). "Dupilumab, an IL-4 and IL-13 inhibitor used in AD treatment, has shown promise in reducing the severity of both AD and COVID-19 by modulating these cytokines." (PMID 40438776, 2025). "Il-13 was recently discovered to be a core driver of COVID-19 severity; patients prescribed Dupliumab, an antibody that blocks IL-13 and Il-4, have significantly less severe disease." (PMID 40429886, 2025). "Asymptomatic individuals exhibited a significantly higher expression of Th2 cytokines compared to patients with moderate and severe COVID-19, specifically IL-5 (p = 0.0444) and IL-13 (p = 0.0389)." (PMID 40266113, 2025). "We also observed that higher levels of IL1β (and to a lesser extent sCD14, IL13, IL17 and TNFα) at 0–4 weeks were strongly associated with ongoing PASC at 24 weeks after COVID-19 onset." (PMID 39008486, 2024). "Using the REAC pathway analysis of differentially expressed genes in COVID-19-positive cases, we detected interleukin IL-2, IL-7, and IL-10 as well as IL-1, IL-4, IL-13, and IL-36." (PMID 38240884, 2024). "IL-13 has emerged as one of the recently identified cytokines as contributors to the severity of COVID-19." (PMID 39172871, 2024). "In contrast, IL-13 was found to be reduced in moderate and severe COVID-19 patients compared to mild COVID-19 patients or healthy controls." (PMID 38855114, 2024). "A closer inspection of the mRNA list unveils another interesting pattern—Th2 supporting cytokines such as IL5 and IL13 are among the most positively upregulated mRNAs in COVID-19 (+) samples." (PMID 38932146, 2024). "Elevated levels of serum type 2 cytokines, including IL-4 and IL-13, were found to be predictive of life-threatening COVID-19 in hospitalized patients." (PMID 37631998, 2023). "Further studies are needed to fully elucidate the mechanisms underlying these observations and to explore the potential therapeutic value of targeting CD74 and IL-13 in COVID-19." (PMID 37568438, 2023). "The reasons for the possible pathogenetic role of endogenous IL-13 in COVID-19 vs. LPS-induced lethality remains to be studied." (PMID 37568438, 2023). "The most relevant cytokines that were significantly associated with mortality in COVID-19 patients were: IFN-β, IL-13, TNF-β, TGF-α, and IL-18/IGIF." (PMID 36851766, 2023). "Consistent with our findings, Donlan and co-workers detected significantly increased IL-13 levels in COVID-19 patients." (PMID 36980378, 2023). "In patients with severe symptoms, COVID-19 manipulates the immune cells to produce a higher amount of IL-13." (PMID 37242334, 2023). "A phase IIa trial demonstrated that dupilumab reduces the probability of admission to the intensive care unit for patients with moderate to severe COVID-19 and improves the survival rate of patients by disabling the signal transduction of IL-4 and IL-13." (PMID 37240520, 2023). "At least three further pathways indicate a strong overlap between neurodegeneration, COVID-19 and inflammation, such as »Interleukin-4 and interleukin-13 signaling«, »Cytokine signaling in immune system«, and »Signaling by interleukins«." (PMID 37008787, 2023).
COVID-19 (continued). "Increased levels of IL-6, IL-13, YKL-40, and KL-6 were associated with mortality in COVID-19 patients." (PMID 36975498, 2023). "Owing to the importance of IL-13 in COVID-19 severity and in regulating several vital biological processes, new molecules that can modulate the cytokine should be exploited." (PMID 37041520, 2023). "IL-13 is a driver of COVID-19 severity, and neutralization of IL-13 reduces the disease in a mouse model." (PMID 37114050, 2023). "Another piece of evidence supporting the activation of Th1 lymphocytes in mild and moderate COVID-19 is the increased serum IL-13 level in these patients." (PMID 37373331, 2023). "SARS-CoV-2 spike proteins that weigh less than 70 kDa can activate Th2 cells, generating a great deal of IL-4 and IL-13, which are elevated in both mild and severe COVID-19 patients." (PMID 37240520, 2023). "Patients that are positive for COVID-19 showed elevated IL-13 levels in the plasma, and it was significantly higher in patients who needed ventilation." (PMID 36851616, 2023). "Plasma IL-13 levels were found to be significantly elevated in COVID-19 patients with severe disease and those requiring mechanical ventilation." (PMID 37631998, 2023). "Supernatants were subsequently analyzed for key inflammatory cytokines associated with the cytokine storm in COVID-19 (IFN-γ, IL-1β, IL-2, IL-4, IL-6, IL-8, IL-10, IL-12p70, IL-13, and TNF-α), using the Meso Scale platform." (PMID 36296272, 2022). "Dupilumab treatment also reduced mortality in mice by attenuating SARS-CoV-2-induced pathological damage, suggesting that IL-13 has a role in exacerbating post-COVID-19 immune damage." (PMID 36362440, 2022). "Although ILC2/IL-13 plays an important role in the pathological changes of COVID-19, the specific regulatory mechanism remains to be further explored." (PMID 36362440, 2022). "In this sense, another interesting finding in the samples collected after two months of SARS-CoV-2 infection in the COVID-19 group with SIgA was not only the increased IL-13 levels but also the positive correlation between IL-13 and IL-17." (PMID 35686128, 2022). "Serum levels of IP-10, CRP, IL-10, IFNγ, IL-13, IL-17α, IL-23, IL-6 were particularly upregulated in COVID-19 patients compared to controls." (PMID 36554094, 2022). "In line with this, using a mouse model of COVID-19, it has been shown that IL-13 promotes severe disease, and that this response is likely to be mediated by the deposition of hyaluronan in lungs." (PMID 35386702, 2022). "Accordingly, previous evidence has reported an increase in the production of IL12 and IL13 in the CSF of COVID-19 patients with neurological manifestations." (PMID 36195636, 2022). "In the present study, we detected significantly higher serum levels of measured cytokines, chemokines, and inflammatory proteins (IP-10, CRP, IFNγ, IL-10, IL-13, IL-17α, IL-23, and IL-6) in COVID-19 patients than in controls." (PMID 36554094, 2022). "Treatment with the IL-13/IL-4 signaling antagonist, dupilumab, significantly reduced pathological damage in COVID-19 patients." (PMID 36362440, 2022). "In intergroup analysis, the COVID-19 groups showed higher salivary levels of IL-10, IL-13, IL-17A, and IFN-α than the control group." (PMID 35686128, 2022). "Serum IP-10, MCP-1, CRP, IFNγ, IL-10, IL-13, IL-17α, IL-23, and IL-6 were significantly higher in COVID-19 patients compared to controls." (PMID 36554094, 2022). "The presence of critical COVID-19 (OR 6.666 [95% CI 1.886–34.481], P=0.002) and serum levels of IL-13 (pg/mL) OR 0.978 [95% CI 0.957-0.997], P=0.028) were the explanatory features of a sustained humoral immune response 6 months after recruitment." (PMID 36045688, 2022). "Lastly, the COVID-19 group without SIgA exclusively showed a positive correlation between IL-12p70 and IL-13, whereas the COVID-19 group with SIgA presented positive correlations between the levels of SIgA and IFN-γ, as well as IL-17A." (PMID 35686128, 2022).
COVID-19 (continued). "The other anti-inflammatory cytokines IL-4 and IL-13 were raised only in recovered post-COVID-19 patients, whereas TGF-β1 remained unchanged in all cases." (PMID 36585712, 2022). "IL-13 and IL-10 as anti-inflammatory cytokines were also significantly elevated in COVID-19 patients." (PMID 34489933, 2021). "During type 2 inflammation in the lung, IL-13 is a significant driver of goblet cell responses, and our data provide evidence that IL-13 signaling is active in COVID-19 but less dramatic, histologically, than in other models of type 2 immunity." (PMID 34185704, 2021). "Using a mouse model of COVID-19, we discovered that IL-13 promotes severe disease, and that this response is likely to be at least partially mediated by the deposition of HA in the lungs." (PMID 34185704, 2021). "Understanding the role of IL-13 and HA has important implications for therapy of COVID-19 and, potentially, other pulmonary diseases." (PMID 34185704, 2021). "Overall, this work in humans and mice implicates IL-13 as an important driver of severe outcomes during COVID-19, in part through HA-CD44 engagement in the lungs." (PMID 34185704, 2021). "In COVID-19 patients who died, blood IL-13 levels significantly decreased while IL-1Ra significantly increased at T3 compared to baseline." (PMID 33767713, 2021). "In contrast, COVID-19 was distinguished by a lymphocyte T cytokine response, as reflected by an increase in IL-2, IL-4, IL-5, IL-7, IL-13, IL-17, and soluble CD40L (sCD40L)." (PMID 35111777, 2021). "Considering the extreme heterogeneity in immune responses to COVID-19, it is unlikely that IL-13 blockade will work in all patients." (PMID 34185704, 2021). "Regarding Th2 cytokines, COVID-19 patients showed higher levels of IL-6, IL-10 and IL-13, but lower levels of IL-4 (p < 0.001, for all of them)." (PMID 33718270, 2021). "At baseline, we found higher levels of blood Th2 inflammatory cytokines (IL-5 and IL-13) in the blood of COVID-19 patients compared to controls." (PMID 33767713, 2021). "Nevertheless, IL-4, IL-5, and IL-13 displayed a trend toward an increase in the clinical scenario of severe COVID-19, and a reason for the interest is the importance of IL-5 to predict mortality, with a predictive value of around 0.73." (PMID 33767626, 2021). "Plasma levels of IL-13 were significantly higher in patients who were positive with COVID-19 compared with uninfected patients, consistent with previous reports." (PMID 34185704, 2021). "The H1N1 group presents a statistically significant higher tissue expression of IL-13 compared to COVID-19 (p = 0.007)." (PMID 33122784, 2020). "This study also reported an increase in IL-13 in COVID-19 patients with brain fog." (PMID 41516418, 2026). "Out of the 17 cytokines tested, nine (IL-1β, IL-2, IL-4, IL-5, IL-12, IL-13, IL-17, granulocyte colony-stimulating factor (G-CSF), granulocyte-macrophage colony-stimulating factor (GM-CSF)) were undetectable in the peripheral blood of COVID-19 patients." (PMID 39408857, 2024). "The higher median IgM, IgA, and IgG1 values in the sera of the MIS-C cohort to some of the COVID-19 Ags may relate to the higher type-2 cytokines (IL-4, IL-5, IL-6, and IL-13) and IL-21 enhanced Tfh activity known to promote B-cell activities." (PMID 38932242, 2024). "COVID-19 was associated with a change in expression of two inflammatory markers, IFN-γ and IL-13." (PMID 39696496, 2024). "In addition, patients who developed COVID-19 while prescribed Dupilumab, a monoclonal antibody that blocks IL-4 and IL-13 signaling, have been shown to have a less severe disease course." (PMID 37568438, 2023). "Although not statically significant, the polar charts show a signal towards the reduction in the production of pro-inflammatory cytokines, and specifically IL-1β, IL-2, IL-12, IL-13, IL-17A secreted by M2 macrophages of COVID-19 patients, after PD1 stimulation." (PMID 37153620, 2023).
COVID-19 (continued). "However, type 2 cytokines, IL-4 and IL-13, are also a key factor in promoting and aggravating COVID-19, and expressions of IL-4 and IL-13 are elevated in the serum of patients with COVID-19." (PMID 37240520, 2023). "Interestingly, a series of COVID-19 related pathways were significantly enriched by RNAenrich, e.g. human interleukin-4 and interleukin-13 signaling (P = 5.74E-14) (P refers to P.adjust), interleukin-6 signaling (P = 8.64E-04), and so on." (PMID 37399102, 2023). "Notably, the decrease in median IL-13 from 0.53pg/mL [IQR: 0.37-1.29] in the TB-only group to 0.50pg/mL [0.17-0.53] in the TB/COVID-19 group had the lowest p-value (p=0.1050)." (PMID 38179046, 2023). "Removing ICAM-1 in the Common Cold cocktail and adding sACE2 resulted in COVID-19 Cocktail A. Removing sIL-4Rα from Cocktail A and adding IL-4 and IL-13 made Cocktail B, whereas adding IL-4 to Cocktail A gave Cocktail C. Adding IL-13 to Cocktail C gave Cocktail D." (PMID 37040185, 2023). "The role of IL13 in COVID-19 severity was also confirmed by other independent studies." (PMID 37041520, 2023). "In addition, we found that cytokines related to TH2 regulations (IL-4, IL-13, IL-33), cell metabolism (lep, lep-R) and interferons (IFNα, IFNβ, IFNγ) were also predictive of life-threatening COVID-19." (PMID 35386702, 2022). "In these studies, local, but not systemic increases of IL-17 were observed in the lung without co-expression of IL-13, where IL-13 has been associated with severe disease progression with COVID-19 in mouse models." (PMID 36322572, 2022). "Few data are available on the quantification of IL-13 in plasma from COVID-19 patients." (PMID 35386702, 2022). "It was previously shown that the lower levels of IFN-α in the blood of seriously ill COVID-19 patients could be accompanied by elevated levels of pro-inflammatory cytokines (IL-5, IL-6, IL-10, and IL-13)." (PMID 36014561, 2022). "When analysis was performed using the O’Brien method and the functional groupings described in the Methods, we found that groups related to TH2 regulations (IL-4, IL-13, IL-33), cell metabolism (lep, lep-R) and interferons (IFNα, IFNβ, IFNγ) were also predictive of life-threatening COVID-19." (PMID 35386702, 2022). "In addition, plasma concentrations of Th2 cytokines IL-4, IL-10 and IL-13 were also significantly upregulated in COVID-19 patients." (PMID 36307516, 2022). "In a different way, whereas IFN-α showed a positive correlation with IL-6 in the control group without SIgA, the IFN-α showed a positive correlation with IL-10 in the control group with SIgA, with IFN-γ in the COVID-19 group with SIgA, and with IL-13 in both COVID-19 groups." (PMID 35686128, 2022). "Ultimately, pathway enrichment analysis (PEA) and Reactome mining results revealed that philanthotoxin could prevent severe lung injury in COVID-19 patients through the remodeling of interleukins (IL-4 and IL-13) and the matrix metalloproteinases (MMPs)." (PMID 35215266, 2022). "These experimental findings lend weight to our epidemiological observation indicating a non-elevated risk of COVID-19-associated hospitalization and mortality under an IL-13 blocking agent, dupilumab." (PMID 34647194, 2022). "A recent proteomic profiling study pointed to DC-SIGN as a mediator of genetic risk in COVID-19 and finally DC/L-SIGN expression is induced by proinflammatory cytokines such as IL-4, IL-6, IL-10 and IL-13, known to be overexpressed in severe SARS and COVID-19 cases." (PMID 34015061, 2021). "In conclusion, knowing that IL-13 is a powerful indicator of COVID-19 severity, interventions that directly inhibit IL-13 activity at the lung mucosae may prove useful in preventing or reducing disease progression." (PMID 34027204, 2021). "In addition, patients who acquired COVID-19 while prescribed Dupilumab, a mAb that blocks IL-13 and IL-4 signaling, had less severe disease." (PMID 34185704, 2021).
COVID-19 (continued). "Collectively, these observations indicate that IL-13 may underpin inflammatory immune cell representations at the lung to drive cytokine storming in patients with COVID-19." (PMID 34027204, 2021). "However, the two studies agree with the increase of fundamentals type 2 cytokines, like IL-5 and IL-13 in severe COVID-19 patients, at least in a subset of them." (PMID 33767626, 2021). "Specifically, IL-13 facilitates airway smooth muscle proliferation, fibroblast proliferation, goblet cell hyperplasia, parenchymal inflammation, and collagen deposition, many of which have been observed in patients with fatal COVID-19." (PMID 34027204, 2021). "Excessive IL-13 at the lung mucosae could be a key determinant of COVID-19-related hyper-inflammation." (PMID 34027204, 2021). "IL-13 levels were elevated in patients with severe COVID-19." (PMID 34185704, 2021). "Studies have revealed that IL-13 is a driver of COVID-19 severity, and could disrupts type 2 pneumocyte stem cell activity." (PMID 34489933, 2021). "Neutralization of IL-13 also resulted in changes to other genes that may be of interest in future studies on the contributions of IL-13 to lung inflammation during COVID-19." (PMID 34185704, 2021). "In the context of COVID-19, a viral vector-based approach to transiently inhibit excess IL-13 at the lung mucosae may help alleviate severe disease similarly to therapies using monoclonal antibodies." (PMID 34027204, 2021). "Moreover, recent data suggest that increased serum concentrations of IL-13 are seemingly correlated to severe COVID-19 outcomes and IL-13 blockade reduced disease severity in a mouse model of SARS-CoV2 infection." (PMID 34177944, 2021). "Moreover, IL-33 is a key upstream mediator of IL-13 at the lung mucosae and is thought to play a role in COVID-19 pathogenesis." (PMID 34027204, 2021). "Because the finding that neutralization of IL-13 during COVID-19 led to reduced HA deposition was potentially novel, we investigated whether IL-13 administration could directly result in increased HA deposition in the lungs of mice." (PMID 34185704, 2021). "Interestingly, the production of cytokines by CD4+ (mainly IL-2 and IFN-γ and trace amounts of IL-4, IL-5, IL-13, or IL-17α) was also reported in COVID-19 convalescents." (PMID 32916812, 2020). "Driven by T helper 2 (Th2) cells and T2 cytokines, such as interleukin 4 (IL-4), IL-5, and IL-13, the T2-high asthma endotype involves eosinophils, which may provide partial protection against COVID-19 by suppressing T1 inflammatory responses and cytokine storms." (PMID 40149651, 2025). "As HA has been demonstrated as a mediator of multiple pulmonary diseases, including pulmonary fibrosis and idiopathic pulmonary hypertension, this led to the hypothesis that IL-13, acting as a regulator of HA matrix formation, may be involved in pulmonary dysfunction after recovery from COVID-19." (PMID 38312212, 2024). "Additionally, IL-13 levels are elevated in severe COVID-19 patients." (PMID 38508309, 2024). "Recent studies have hypothesized that IL13 may be a driver of COVID-19 severity." (PMID 38932146, 2024). "In addition, TGFβ1, TGFβ3, IL-6, and IL-10 may be influential biomarkers of COVID-19 severity during the early phase of infection, whereas Th2 cytokines, IL-4 and IL-13, may be markers of persisting severity." (PMID 37569646, 2023). "However, recent studies demonstrated that the levels of IL-13 were significantly higher among COVID-19-positive patients as compared to their uninfected counterparts, as well as among COVID-19 patients requiring mechanical ventilation relative to milder COVID-19 patients." (PMID 34647194, 2022). "Based on the basic pathological features of COVID-19, which include dysregulation of the lung mucosa and the massive production of mucus, it is reasonable to speculate that IL-13 is likely to be closely related to the pathological progression to severe COVID-19." (PMID 36362440, 2022).